GPN2 (GPN-loop GTPase 2)
Description:
Small GTPase involved in the correct assembly of RNA polymerase RNA polymerase II and III (RNAPII and RNAPIII) complexes, ensuring their proper nuclear import.
Synonyms: ATPBD1B; FLJ10349
Tractability: No criterion of Open Targets' tractability assessment is met for any kind of drug.
Gene: Protein-coding gene on chromosome 1 (26,876,132 to 26,890,283, reverse strand). Ensembl gene ENSG00000142751.
Subcellular location: Cytoplasm
Gene Ontology:
Molecular function: protein binding; GTPase activity
Cellular component: cytoplasm
Genetic constraint (gnomAD): Loss-of-function variants: 20 observed, 23.86 expected, observed/expected ratio (o/e) 0.84, 90% interval 0.59 to 1.22. The upper end of that interval is the gene's LOEUF score, 1.22, which puts it in group 5 of 6, group 1 being the genes least tolerant of losing a copy. Missense variants: 363 observed, 362.75 expected, observed/expected ratio (o/e) 1, 90% interval 0.92 to 1.09. Synonymous variants: 189 observed, 157.9 expected, observed/expected ratio (o/e) 1.2, 90% interval 1.06 to 1.35.
Homologues: Orthologues: chimpanzee GPN2 (99% identical), macaque GPN2 (99% identical), dog GPN2 (98% identical), mouse Gpn2 (96% identical), pig GPN2 (96% identical), guinea pig GPN2 (96% identical), rat Gpn2 (95% identical), zebrafish gpn2 (71% identical), Drosophila melanogaster CG10222 (47% identical), Caenorhabditis elegans B0207.6 (37% identical). Paralogues in human: GPN3 (37% identical), GPN1 (23% identical).
Diseases named in the same sentence as GPN2 in open-access papers:
GPN2 is named in the same sentence as 1 disease in open-access papers, as found by Europe PMC text mining. Sharing a sentence is not in itself a finding about the gene and the disease. The quoted sentences say what the papers report.
cancer (2 papers, 2019 to 2024). A tumor composed of atypical neoplastic, often pleomorphic cells that invade other tissues. "Given that genomic instability is a hallmark of cancer, GPN2 may also have potential implications in cancer development." (PMID 39642114, 2024).